PATE2 (prostate and testis expressed 2)
Synonyms: PATE-M; C11orf38; UNQ3112; LVLF3112
Tractability: Antibody: UniProt places it where antibodies can reach, with high confidence; UniProt predicts a signal peptide or a membrane-spanning region; its Gene Ontology location is reachable by antibodies, with medium confidence.
Gene: Protein-coding gene on chromosome 11 (125,776,113 to 125,778,828, reverse strand). Ensembl gene ENSG00000196844.
Subcellular location: Secreted
Gene Ontology:
Cellular component: extracellular region
Genetic constraint (gnomAD): Loss-of-function variants: 9 observed, 13.82 expected, observed/expected ratio (o/e) 0.65, 90% interval 0.39 to 1.14. The upper end of that interval is the gene's LOEUF score, 1.14, which puts it in group 4 of 6, group 1 being the genes least tolerant of losing a copy. Missense variants: 133 observed, 143.13 expected, observed/expected ratio (o/e) 0.93, 90% interval 0.81 to 1.07. Synonymous variants: 44 observed, 49.44 expected, observed/expected ratio (o/e) 0.89, 90% interval 0.7 to 1.14.
Homologues: Orthologues: chimpanzee PATE2 (99% identical), macaque PATE2 (78% identical), rabbit PATE2 (70% identical), dog PATE2 (67% identical), rat Pate2 (65% identical), pig PATE2 (64% identical), mouse Pate2 (60% identical), guinea pig PATE2 (59% identical). Paralogues in human: ACRV1 (21% identical), PATE3 (19% identical), PATE4 (17% identical), PATE1 (16% identical).